OCLN (occludin)
Diseases named in the same sentence as OCLN in open-access papers (continued):
Sharing a sentence is not in itself a finding about the gene and the disease.
Hyperglycemia (continued). "Active hyperglycemia-induced demethylation of ROBO4 also affected ZO-1 and occludin expression." (PMID 37430272, 2023). "Through Azilsartan treatment, we found that the enhanced BBB or endothelial monolayer permeability and the downregulated occludin were significantly reversed, indicating a potential protective effect of Azilsartan against BBB disruption induced by hyperglycemia." (PMID 34266350, 2021). "Although there is no data available on expression of podocyte occludin in response to hyperglycemia, its expression is presumably elevated." (PMID 24244596, 2013). "The effects of hyperglycemia on DNA methyltransferase 1, Tet methylcytosine dioxygenase 2 (TET2), 5-methylcytosine, 5-hydroxymethylcytosine, and the binding of TET2 and SP1 to the ROBO4 promoter, as well as the expression of ROBO4, zonula occludens 1 (ZO-1) and occludin were examined." (PMID 37430272, 2023).
glioma (21 papers, 2013 to 2025). A benign or malignant brain and spinal cord tumor that arises from glial cells (astrocytes, oligodendrocytes, ependymal cells). "It has been shown that occludin is downregulated and subsequently phosphorylated in human high-grade gliomas, thus causing increased permeability of the TJs as a result of the altered interaction between phosphorylated occludin and ZO1, ZO2 and ZO3." (PMID 30983966, 2019). "In gliomas, there is a noticeable dysregulation of claudins, occludin, and zonula occludens-1 abundance, and their dislocation has been observed." (PMID 39963115, 2025). "In this research, protein expression of Occludin in ileum and colon tissues were down-regulated in glioma mice, which means intestinal barrier was damaged." (PMID 36147842, 2022). "Studies with human glioma endothelial cells showed that overexpression of miR-181a-5p reduces endothelial resistance and the gene expression of tight junction molecules OCLN, ZO-1 and CLDN-5." (PMID 33001231, 2021). "KLF4 is supposed to be crucial for the integrity of the blood-tumor barrier because it enhances the promoter activities of tight junction proteins (TJPs), including ZO-1, occludin, and Claudin5 in the glioma endothelial cells." (PMID 32264912, 2020). "Some studies of glioma have shown that MMP expression or activation is related to the downregulation of occludin in the BBB, which leads to destruction of the BBB." (PMID 32884584, 2020). "In contrast, silencing of miR-153 or miR-377 increased the expressions of ZO-1, occludin, and claudin-5 and decreased the permeability of glioma-conditioned normal BBB." (PMID 30305135, 2018). "We found that MIR17HG was highly expressed in GECs and MIR17HG silencing decreased the expressions of ZO-1, occludin, and claudin-5 and increased the permeability of glioma-conditioned normal BBB." (PMID 30305135, 2018). "Overexpression of piR-DQ590027 down-regulated the expressions of ZO-1, occludin, and claudin-5 and increased the permeability of glioma conditioned normal BBB." (PMID 30305135, 2018). "The present study demonstrated that FOXR2 had high expression in GECs, and silencing of FOXR2 decreased the expressions of ZO-1, occludin, and claudin-5 and increased the permeability of glioma-conditioned normal BBB." (PMID 30305135, 2018). "Overexpression of miR-153 or miR-377 reduced the expressions of ZO-1, occludin, and claudin-5 and further increased the permeability of glioma-conditioned normal BBB." (PMID 30305135, 2018). "FOXC1 decreased BTB permeability by increasing the promoter activity and expression of ZO-1 and occludin, and promoted glioma angiogenesis by increasing the promoter activity and expression of chemokine (C–X–C motif) receptor 7b (CXCR7)." (PMID 28287613, 2017). "Western blot analysis of tumor tissue was performed to analyze the expression of proteins involved with peritumoral edema and glioma progression including the tight junction proteins, ZO-1 and occludin, as well as the water channeling proteins, AQPN-1, AQPN-4." (PMID 26083629, 2015). "Occludin is vital for maintaining tight junctions between cells during vascular development and the integrity of the BBB, which suggests that a reduction in occludin may be involved in NVU functional alterations in gliomas." (PMID 37174724, 2023). "This knockdown also decreased the levels of tight junction-correlated proteins, such as Zonula occludens 1 (ZO-1), occludin, and claudin-5, in glioma microvascular endothelial cells by targeting upstream stimulatory factor 1 (USF1), thus enabling drug delivery." (PMID 33980320, 2021). "Thus, knockdown of this lncRNA reduces expression of tight junction proteins, such as ZO-1, occludin, and claudin-5 in glioma microvascular endothelial cells." (PMID 33980320, 2021). "In addition, KLF4 is shown to regulate the integrity of blood-tumor barrier via enhancing the promoter activities of TJPs including ZO-1, occludin, and Claudin5 in the glioma endothelial cells." (PMID 32264912, 2020).
glioma (continued). "This study showed that piR-DQ590027 was lowly expressed in glioma-conditioned ECs (GECs) and that piR-DQ590027 overexpression could decrease the expressions of ZO-1, occludin, and claudin-5 to further increase the permeability of glioma-conditioned normal BBB." (PMID 30305135, 2018). "Moreover, down-regulation of FOXR2 inhibited transcription and decreased the expressions of ZO-1, occludin and claudin-5, and further increased the permeability of glioma-conditioned normal BBB." (PMID 30305135, 2018). "Moreover, downregulation of FOXR2 decreases the transcription and thus the expressions of ZO-1, occludin, and claudin-5, and thereby increases the permeability of glioma-conditioned normal BBB." (PMID 30305135, 2018). "However, piR-DQ590027 silencing increased the expressions of ZO-1, occludin, and claudin-5 and thus reduced the permeability of glioma-conditioned normal BBB." (PMID 30305135, 2018). "Silencing of FOXR2 expression significantly decreased the mRNA and protein expression of ZO-1, occludin, and claudin-5, reduced their distribution in the cell membrane, and increased the permeability of glioma-conditioned normal BBB; FOXR2 overexpression had the opposite effects." (PMID 30305135, 2018). "HOX transcript antisense intergenic RNA (HOTAIR) is up-regulated in gliomas, and HOTAIR combines with the promoter regions of occludin, ZO-1, and claudin-5 to promote their expressions, which decreases BBTB permeability." (PMID 33767583, 2021). "Finally, piR-DQ590027 is poorly expressed in glioma-conditioned ECs whereas piR-DQ590027 over-expression could decrease ZO-1, occludin, and claudin-5 expression to further increase glioma-conditioned normal BBB permeability through the piR-DQ590027/MIR17HG/miR-153(miR-377)/FOXR2 pathway." (PMID 31399034, 2019). "Previous study suggested that NEAT1 was upregulated in glioma endothelial cells (CECs), knockdown of NEAT can increased blood-tumor barrier permeability through reducing the expression of TJ related proteins including ZO-1, Occludin, Claudin-5." (PMID 40338929, 2025). "The immunostaining results revealed a significantly reduced number of occludin-positive cells in the brain with glioma compared to the normal brain, with a decrease of 71.60%." (PMID 37723574, 2023). "The expression of miR-181a is increased in glioma, and miR-181a can inhibit Kruppel-like factor 6 (KLF6) mRNA expression by directly binding to the 3' UTR of KLF6 mRNA; KLF6 can promote the transcriptional expressions of ZO-1, occludin, and claudin-5 mRNAs." (PMID 33767583, 2021). "Our study showed that piR-DQ590027 can decrease the expression of ZO-1, claudin-5, and occludin and increase the permeability of glioma-conditioned normal BBB, suggesting that piR-DQ590027 overexpression increases the permeability of glioma-conditioned normal BBB via the paracellular pathway." (PMID 30305135, 2018). "Moreover, FOXC1 presented a negative expression pattern with miR-137 in GECs, which promoted ZO-1 and occludin expression, led to an increase in BTB permeability, and promoted CXCR7 expression that activated glioma angiogenesis." (PMID 28287613, 2017). "Glioma C6 CM did not alter the expression of occludin and claudins 1 and 3 in ReNcells CX, butdecreased the amount of claudin-4." (PMID 23637756, 2013). "It is conceivable, that in gliomas high levels of HDAC4 expression in complex with MEF2 acts as transcriptional repressor of KLF4 and, consequently, of zonula occluden-1, claudin-5, and occludin gene expression, which may be another important component in the mechanism of BBB disruption in gliomas." (PMID 30837601, 2019). "The results indicate that piR-DQ590027 overexpression increases the permeability of glioma-conditioned normal BBB via the paracellular pathway by reducing the expressions of ZO-1, occludin, and claudin-5 in a manner that is related to the negative regulation of MIR17HG expression." (PMID 30305135, 2018).
lung carcinoma (21 papers, 2014 to 2025). "The expression of ZO-1, Occludin and Claudin-1 protein in lung cancer mice were detected, and the repair effect on the intestinal mucosal physical barrier in lung cancer mice was investigated." (PMID 36992837, 2023). "Inhibition of Occludin led to decreased cell proliferation, invasion, migration and induced apoptosis in lung cancer cells." (PMID 35642021, 2022). "OCLN expression increases on A549 lung cancer cells promote their resistance to cisplatin, doxorubicin, and gemcitabine." (PMID 34142021, 2021). "As an anticancer drug resistance mechanism, there is an increased expression of OCLN in the TJs of lung cancer cells." (PMID 34142021, 2021). "Another study reported that OCLN overexpression stimulates malignant growth of lung cancer cells, thereby promoting proliferation and blocking apoptosis." (PMID 34142021, 2021). "Elevated levels of occludin, a transmembrane protein present in TJs, have been observed as melatonin effectively counteracted the migration of a human lung cancer cell line, A549." (PMID 28420185, 2017). "After overexpressing TMEM17, levels of p-ERK and its downstream molecules, p-P90RSK and Snail, were down-regulated, while levels of Occludin and Zo-1 were up-regulated, which result in the inhibition of invasion and migration ability of lung cancer cells." (PMID 29050311, 2017). "In lung cancer cells, the expression of E-cadherin and occludin was upregulated in Slug-knockdown cells, a relationship opposite that observed under Daxx-knockdown conditions, implying that Daxx effects Slug-mediated cell invasion." (PMID 28004751, 2016). "In vitro studies showed that basal half-life of Occludin was about ∼6 hours in primary human brain microvascular cells and basal half-life of Claudin-1 was also about ∼6 hours in human lung carcinoma cell line A549 cells." (PMID 24845399, 2014). "In addition, OCLN knockdown promoted apoptosis of lung cancer cell lines and reduced their ability to invade, on the basis of which the role of OCLN as a tumor promoter and prometastatic factor was shown for the first time." (PMID 36768739, 2023). "According to the literature, high expression of OCLN has been found in lung cancer, and when OCLN was knocked down in cell lines of lung cancer (A549, NCL-H1650, SPC-A1, HCC827, NCI-H1299, and MSTO-211H), inhibition of cell proliferation was observed in vitro and in vivo." (PMID 36768739, 2023). "It shows that lung disease can affect the intestine; lung cancer can reduce the protein expression of ZO-1, Occludin and Claudin-1 in the colon tissue of mice, and ZSP can inhibit this protein expression change in the colon tissue caused by the pathological transformation of the lung and intestine." (PMID 36992837, 2023). "In addition, it was suggested that CPT and TanIIA might inhibit miR-21-5p to promote occludin protein expression, thereby refining the tight junction structure of tumour vascular endothelial cells and inhibiting metastasis of lung cancer cells." (PMID 38129556, 2023). "Five of the eight NSCLC/lung cancers harboring a RASGRF fusion were adenocarcinomas (corresponding to the NSCLCs containing PACSIN2-RASGRF1, DLG1-RASGRF1, RP2-RASGRF1, NPTN-RASGRF1, and OCLN–RASGRF2)." (PMID 40615519, 2025). "Moreover, the changes in Occludin and E-cadherin were further examined by IF, pointing that circDENND4C might change the metastatic ability of lung cancer cells via targeting the miR-200b/MMP-9 axis, further acting on the proteins of cell adhesion and tight junction." (PMID 40034591, 2025). "Profiling the epithelial‐mesenchymal transition‐related molecular markers demonstrated decreased CDH1, TJP1, and OCLN and increased ZEB1, FN1, and EZH2 in response to CDKN2A silencing in lung cancer cells." (PMID 33155773, 2020).
lung carcinoma (continued). "We observed that the expression of pro-EMT markers was downregulated while expression of anti-EMT markers, occludin and E-cadherin, was substantially increased upon the exposure to 50 and 100 μM BGM in lung cancer cells." (PMID 30004418, 2018). "In the A549 lung cancer cell line, OCLN knockdown was not related directly to their resistance to anticancer drugs, yet it suppressed their chemosensitivity on a multicellular spheroid assay." (PMID 34142021, 2021). "To examine whether the induction of EMT reduces HER2 expression, we analyzed mRNA expression of ERBB2, epithelial phenotype markers CDH1, EPCAM, MUC1 and OCLN, mesenchymal phenotype markers CDH2, FN1, SNAI2, and VIM in the A549 cell line (HER2-high human lung cancer epithelial cell line)." (PMID 34575017, 2021). "OCLN may not be related to cancer drug resistance acquisition directly, but it limits the chemosensitivity of anticancer drugs to lung cancer cells." (PMID 34142021, 2021).
colon carcinoma (20 papers, 2010 to 2025). "Our work further connects high MMP-7 and MMP-9 expression to occludin degradation, loss of tight junctions and tumor cell budding in colon cancer." (PMID 29731961, 2018). "For example, 6 of 7 studies analyzing between 12 and 127 colon cancers reported occludin positivity rates between 91.6 and 100% (our study: 99.1%)." (PMID 40173205, 2025). "In these studies, the range of reported occludin positive cases ranged from 37.3 to 100% in colon cancer, from 52.8 to 98% in serous ovarian cancer, and from 8.7 to 70.2% in oral squamous cell carcinoma." (PMID 40173205, 2025). "In a few instances, including expression of claudin 7 in CMS3 colon cancers and expression of occludin in CMS1 and CMS3 colon cancers, upregulation was observed in APC-mutated cases, implying a central role of the WNT/β-catenin cascade in these cases." (PMID 37998722, 2023). "Genomically identified groups of colon cancer displayed distinct regulation of claudins and occludin at the mRNA level." (PMID 37998722, 2023). "The protein expression levels of ZO-1 and occludin were significantly reduced in colon tissue after colon cancer modelling (p < 0.01)." (PMID 34531745, 2021). "In previous work, the intestinal intercellular structural integrity was found to be related to tight junction proteins, such as occludin and claudin, in the Caco-2 human colon carcinoma cell line." (PMID 31815958, 2019). "By contrast, in the adenomas and adenocarcinomas, occludin was heterogeneously overexpressed in multifocal areas, including the colon tumor surface." (PMID 29163827, 2017). "The altered occludin immunoreactivity in the ACF lesions was similar to that in the colon tumor tissues." (PMID 29163827, 2017). "Our method detected the altered expression of occludin even in tiny proliferating lesions, similar to the findings in colon tumor tissues." (PMID 29163827, 2017). "Occludin was shown to be frequently downregulated in gastrointestinal tumors and a decreased expression of claudin-1 was observed in breast and colon cancer." (PMID 24348776, 2014). "We have earlier shown disturbed protein expression of Beta-catenin, E-cadherin, occludin and claudin 2 compared to normal surrounding mucosa in colon carcinoma." (PMID 23675182, 2010). "DMOG inhibits the metastasis of colon cancer cells through the occludin-p38 pathway." (PMID 40379610, 2025). "Interestingly, a previous study demonstrated that while BECLIN-1 knockdown disrupted OCCLUDIN trafficking, it unexpectedly reduced TJ permeability in Caco-2 colon cancer cells grown in 2D cultures." (PMID 40395982, 2025). "Expression of claudins 1 to 7 and occludin varied in molecular types of colon cancers in TCGA." (PMID 37998722, 2023). "Colon cancers from genomic studies with publicly available data were examined to define the expression and regulation of the major tight junction proteins claudins and occludin in genomic groups." (PMID 37998722, 2023). "It was observed that TGFβ stimulation increased the levels of MnSOD, fibronectin, vimentin, MMP-9, and N-cadherin and decreased the levels of occludin and E-cadherin in colon cancer cells above the basal level, indicating the mesenchymal-phenotype of these cells is promoted by TGFβ." (PMID 35883447, 2022). "The progression of colon cancer is closely related to decreased occludin and ZO-1." (PMID 34684488, 2021). "Thus, the reduced level of occludin was critical for the formation of spheroids of colon cancer and breast adenocarcinoma." (PMID 33291824, 2020). "Moreover, genetic knockdown of occludin in human colon cancer cells (Caco-2) promote the disruption of tight junctions and barrier dysfunction after exposure to acetaldehyde." (PMID 30845647, 2019). "Two frequently altered pathways in colon cancer, TGFβ/SMAD and WNT/β-catenin, have been shown to possess clusters of regulatory sites in promoters of claudins 1 to 7 and occludin." (PMID 37998722, 2023).
colon carcinoma (continued). "Since the expression of MnSOD is associated with the regulation of EMT, the expression of mesenchymal markers (fibronectin, vimentin, and N-cadherin), epithelial markers (occludin and E-cadherin), and MMP-9 was examined in three colon cancer cell lines." (PMID 35883447, 2022). "CMS4 was characterized by suppression of claudin 2, claudin 3, claudin 7, and occludin and upregulation of claudin 5 mRNAs, not aligning with any of the three TCGA genomic groups or with CMS2 despite the similarities in the prevalence of common colon cancer mutations." (PMID 37998722, 2023).
Crohn disease (20 papers, 2012 to 2025). A gastrointestinal disorder characterized by chronic inflammation involving all layers of the intestinal wall, noncaseating granulomas affecting the intestinal wall and regional lymph nodes, and transmural fibrosis. "In patients with Crohn’s disease, proteins such as Occludin, Claudin-3, -5, -8 are notably decreased and redistributed." (PMID 41031160, 2025). "Patients with Crohn’s disease have low occludin levels and severely compromised tight junction integrity." (PMID 34681392, 2021). "Another example is herb-partitioned moxibustion, which can promote occludin, claudin-1, and ZO-1 expression, and recover the increased epithelial permeability in Crohn’s disease model rats." (PMID 30609730, 2019). "Clinical studies showed that, in patients with Crohn’s disease (CD), the expression of claudin-3 and occludin was decreased." (PMID 29280945, 2017). "Such reduction of Occludin results in increased permeability of the barrier, which might contribute to the development of conditions such as Crohn’s disease." (PMID 40831561, 2025). "Moreover, both occludin and claudin-8 were shown to be downregulated and redistributed from the cellular junctions in patients with active Crohn’s disease." (PMID 38334616, 2024). "For example, TNF-α, which is critical to Crohn’s disease pathogenesis, impairs gut barrier integrity via MLC phosphorylation and occludin internalization." (PMID 31182728, 2019).